ENSG00000302090 (novel transcript)
Gene: Long non-coding RNA gene on chromosome 6 (26,768,576 to 26,780,254, reverse strand). Ensembl gene ENSG00000302090.
Gene Ontology:
Molecular function: triplet codon-amino acid adaptor activity
Biological process: translation